CXorf49C (chromosome X open reading frame 49C)
Gene: Protein-coding gene on chromosome X (71,667,542 to 71,671,527, forward strand). Ensembl gene ENSG00000283599.
Homologues: Orthologues: mouse Gm4779 (38% identical), rat Cxhxorf49 (38% identical), mouse 4933412E24Rik (35% identical), mouse 8030474K03Rik (35% identical), rat Cxhxorf49B (33% identical), rat 4933412E24Rikl (33% identical), rat Cxhxorf49l1 (31% identical), mouse Gm3858 (31% identical). Paralogues in human: CXorf49 (72% identical), CXorf49B (72% identical).